WBP2 (WW domain binding protein 2)
Diseases named in the same sentence as WBP2 in open-access papers (continued):
Sharing a sentence is not in itself a finding about the gene and the disease.
glioma (continued). "We assessed changes in PI3K/Akt signaling under conditions of WBP2 overexpression and WBP2 silencing in glioma cells." (PMID 29497031, 2018). "We screened two potential partner proteins, ENO1 and Homer3, that showed high coverage with WBP2; their corresponding genes are vital in the development of glioma and the nervous system, respectively." (PMID 29497031, 2018). "The expression pattern of WBP2 in several tumor cells was determined, clarifying the carcinogenic action of WBP2 in glioma cells." (PMID 29497031, 2018). "To evaluate the potential impact of WBP2 on cell growth in glioma cells, we induced stable overexpression of WBP2 in U251 and U87 cells (EGFP-Vector and EGFP-WBP2 cell lines)." (PMID 29497031, 2018). "3-(4,5-dimethylthiazol-2-yl)-2,5-diphenyltetrazo-liumbromide (MTT) assay results suggested that upregulation of WBP2 enhanced cell proliferation of glioma cells, while depletion of WBP2 inhibited cell proliferation." (PMID 29497031, 2018). "The immunohistochemistry results showed that WBP2 was highly expressed in 68% of the glioma samples." (PMID 29497031, 2018). "To determine the clinical significances of WBP2 in patients with brain and CNS cancer, we performed data mining and analyzed WBP2 mRNA expression pattern from the publicly available Oncomine database." (PMID 29497031, 2018). "Based on the Ramaswamy Multi-Cancer Statistics (20 of 169 samples was brain and CNS cancer cases), WBP2 was observably upregulated in brain and CNS cancer in comparison with other types of cancer." (PMID 29497031, 2018). "The GRAM domain within the N-terminal of WBP2 serve as Rab-like GTPase activators, and our experiments focus on the crucial role of WBP2 in the development of glioma." (PMID 28724435, 2017). "The data showed that WBP2 promotes proliferation and metastasis of glioma cells by affecting the Embden–Meyerhof pathway (unpublished data)." (PMID 28724435, 2017). "Furthermore, a mass spectrometry analysis performed on glioma cells also identified VASP to be a putative binding partner of WBP2." (PMID 34831354, 2021). "In addition, Homer protein 3 (HOMER3), a member of HOMER, together with WW domain binding protein 2 (WBP2) plays a significant role in glioma invasion." (PMID 33969375, 2021). "Homer3 has been shown to directly interact with WW domain-binding protein 2 (WBP2) in glioma cells." (PMID 32070057, 2020). "Because of its expression pattern in glioma cell lines, we suspected WBP2 may act as a carcinogenic gene in glioma." (PMID 29497031, 2018). "WBP2 is characterized as a particular cancer-promoting feature of glioma cells." (PMID 29497031, 2018). "In summary, we illustrated the carcinogenetic effect of WBP2 in glioma development." (PMID 29497031, 2018). "However, the cross-talk between ENO1, Homer3, and WBP2 remains poorly understood in the progression of glioma." (PMID 29497031, 2018). "Furthermore, in vitro and in vivo experiments indicated that the oncogenic role of WBP2 in glioma was through modulating ENO1 and glycolysis activity via the ENO1-PI3K/Akt signaling pathway." (PMID 29497031, 2018). "To validate the expression pattern of WBP2 in wild-type glioma, we excluded the 20 specimens with IDH1/2 mutation and found that WBP2 was highly expressed in 78.2% of wild-type glioma samples (43/55), in which 36 samples defined as grade III glioma presented high WBP2 expression." (PMID 29497031, 2018). "Therefore, our data confirm that interactions between ENO1, Homer3, and WBP2 potentially mediate the cancer-promoting effects initiated by upregulation of WBP2 in glioma cells." (PMID 29497031, 2018). "Our data indicated that ENO1 and Homer3 had high coverage rates with WBP2, and previous studies have confirmed that both ENO1 and Homer3 are associated with glioma and nervous system development, suggesting these two proteins are an integral part in WBP2-mediated glioma cell growth and metastasis." (PMID 29497031, 2018).
glioma (continued). "To explore the correlation between WBP2 and ENO1 activity, we determined the ENO1 values in six groups of glioma cells (EGFP-Vector, EGFP-WBP2, WBP2 + siNC, WBP2 + siENO1, WBP2 + siWBP2, and WBP2 + siHomer3)." (PMID 29497031, 2018). "We found that forced expression of WBP2 promoted, while limited expression of WBP2 inhibited, ENO1 expression and its downstream PI3K/Akt signaling pathway in glioma cells." (PMID 29497031, 2018). "In short, our findings illustrate that WBP2 modulates the expression and activity of ENO1 and further mediates EMP pathway activity through the PI3K/Akt signaling pathway, to regulate the biologic behavior of glioma cells." (PMID 29497031, 2018). "We also revealed how WBP2 promotes cell proliferation and regulates the cell cycle by modulating ENO1 activity and the ENO1-PI3K/Akt signaling pathway by binding to ENO1 and Homer3 in glioma cells." (PMID 29497031, 2018). "To assess whether WBP2 was involved in the progression of glioma, we performed pulldown/MS analysis using recombinant GST-WBP2 protein as a bait to screen for partners of WBP2 in U251 cells, identifying some potential proteins precipitated with GST-WBP2." (PMID 29497031, 2018).
lung carcinoma (4 papers, 2021 to 2022). "WBP2 acts as a competitive inhibitor by binding to the WW domain of WWC3 protein in lung carcinoma cells to limit WWC3–LATS1 association." (PMID 34831354, 2021). "In lung cancer cells, all three PY motifs of WBP2 are required for association with the WW domain of WWC3." (PMID 34831354, 2021). "At present, the underlying mechanism through which WBP2 affects the biological function of lung cancer cells remains unclear." (PMID 33837178, 2021). "Notwithstanding that WBP2 has been implicated in the Hippo pathway in at least four different cancer types, including breast, gastric, skin and lung cancers, by independent groups, further studies of the interplay are required to clarify the role of WBP2 in the Hippo pathway." (PMID 34831354, 2021). "In addition, gain- and loss-of-function experiments revealed that WBP2 could significantly promote the proliferation and invasion of lung cancer cells both in vivo and in vitro." (PMID 33837178, 2021). "To determine whether WBP2 has a specific role in NSCLC, we first detected the expression of WBP2 in lung cancer specimens, and further assessed the association of this expression with the survival and prognosis of patients via immunohistochemistry and immunofluorescence staining." (PMID 33837178, 2021). "We determined that WBP2 was highly expressed in lung cancer specimens and cell lines and that this expression was closely related to the advanced pTNM stage, lymph node metastasis, and poor prognosis of patients." (PMID 33837178, 2021). "Compared with the normal bronchial epithelial cell line HBE, WBP2 was highly expressed in the four lung cancer cell lines (n = 5)." (PMID 33837178, 2021). "Accordingly, western blot analyses revealed that the expression level of WBP2 was significantly higher in lung cancer tissues than that observed in adjacent tissues (14/16, P < 0.05)." (PMID 33837178, 2021). "However, the underlying cause of high WBP2 expression in lung cancer remains unclear." (PMID 33837178, 2021). "Furthermore, WBP2 has been recently shown to associate with LATS2 and WWC3 to inhibit the Hippo tumor suppressor pathway in gastric and lung cancers, in turn limiting cancer proliferation and invasion." (PMID 34197030, 2022). "However, the expression and potential molecular mechanisms of WBP2 in the context of lung cancer are not fully understood." (PMID 33837178, 2021). "In addition, we observed that WBP2 overexpression promoted the migration and invasiveness of lung cancer cells." (PMID 33837178, 2021). "Therefore, combined with in vivo and in vitro experimental results, we can conclude that WBP2 functions as a tumor-promoting factor when exerting its potential biological functions in lung cancer cells." (PMID 33837178, 2021). "Regarding the high WBP2 expression in lung cancer, it remains unclear whether this is related to the amplification of the gene promoter, transcription level, or post-translation regulation." (PMID 33837178, 2021). "However, both the expression pattern of WBP2 in lung cancer and the ability of this protein to regulate the activity of the Hippo pathway in an indirect manner that is dependent upon YAP remain unreported." (PMID 33837178, 2021). "Next, we examined changes in the biological functions of lung cancer cells after WBP2 knockdown." (PMID 33837178, 2021). "Interestingly, we observed that WBP2 was localized within the cytoplasm of lung cancer cells, and accordingly, we speculated that WBP2 may modulate the Hippo pathway in a YAP-indirect-dependent manner." (PMID 33837178, 2021). "Combined with the implicated role of TAZ in lung cancer, the crosstalk between WBP2 and TAZ in lung cancer also warrants further investigation." (PMID 33837178, 2021). "Furthermore, confocal laser scanning revealed a co-localization of WBP2 and WWC3 in the cytosol of lung carcinoma cells." (PMID 34831354, 2021).
Breast Invasive Carcinoma (3 papers, 2018 to 2022). "WBP2 is observed to be frequently amplified in 25 out of 32 cancer types, and of which, patients with breast invasive carcinoma (BRCA) have the highest frequency of WBP2 amplification, closely followed by liver and uterine cancers." (PMID 34197030, 2022).
colorectal cancer (3 papers, 2020 to 2022). A primary or metastatic malignant neoplasm that affects the colon or rectum. "As WBP2 aberrations can also occur on the protein level, we analyzed the relationship between WBP2 mRNA and protein expression in individual patients of the following three cancer types, BRCA, ovarian cancer (OV), and colorectal cancer (COADREAD)." (PMID 34197030, 2022).
gastric cancer (3 papers, 2018 to 2022). A primary or metastatic malignant neoplasm involving the stomach. "In the study of gastric cancer cells, knockout of WBP2 increased p-YAP, which resulted in the retention of YAP in the cytoplasm, inhibited the cross-linking process of YAP-Tead, and finally down-regulated the expression of TEAD target genes CTGF and CYR61." (PMID 36288272, 2022). "For instance, a series of biochemical experiments in gastric cancer cells revealed that the C terminus of WBP2 is responsible for binding to the C terminal kinase domain of LATS2." (PMID 34831354, 2021). "In lung and gastric cancers, WBP2 has been shown to be a promoter of LATS1/2 kinase activities through interactions with critical regulatory components to inactivate Hippo signalling." (PMID 34831354, 2021). "In the context of lung and gastric cancers, WBP2 has been shown to negatively regulate LATS1 and LATS2 kinase activity through WW domain-dependent and WW domain-independent mechanisms, respectively." (PMID 34831354, 2021). "In a similar fashion, elevated WBP2 protein expression was also observed in the more aggressive gastric cancer cell lines as compared to the less aggressive ones." (PMID 34831354, 2021). "On the other hand, WBP2 may bind directly to LATS2 to bring about inhibition of LATS2 phosphorylation and YAP/TEAD activity in gastric cancer cells, as reported by our laboratory." (PMID 34831354, 2021).
hearing loss (3 papers, 2016 to 2020). "We demonstrate for the first time a direct link between the Wbp2 mutation and progressive hearing loss." (PMID 26881968, 2016). "In order to investigate the functional link between hormonal signalling and hearing impairment and identify new targets for therapies, we used Wbp2‐deficient mice as a genetic tool." (PMID 26881968, 2016). "In order to investigate the functional link between hormonal signalling and hearing impairment and identify new targets for therapies, we analysed Wbp2‐deficient mice." (PMID 26881968, 2016). "Following biochemical characterization of WBP2 resulting in the knowledge of its binding partners and involvement in steroid signaling, WBP2 has since been discovered to play roles in a variety of human diseases such as hearing loss and infertility." (PMID 32393834, 2020). "We have demonstrated a clear link between the Wbp2 mutation and hearing loss." (PMID 26881968, 2016).
triple-negative breast carcinoma (3 papers, 2022 to 2024). An invasive breast carcinoma which is negative for expression of estrogen receptor (ER), progesterone receptor (PR), and human epidermal growth factor receptor 2 (HER2). "As WBP2 can influence the phosphorylation of AKT, circPRKCI sponges miR-545-3p, upregulates the expression of WBP2, activates the PI3K/AKT signaling pathway, and participates in the proliferation and migration of triple-negative breast cancer cells." (PMID 38741779, 2024).
Alzheimer disease (2 papers, 2020 to 2022). A progressive, neurodegenerative disease characterized by loss of function and death of nerve cells in several areas of the brain leading to loss of cognitive function such as memory and language. "Several pathways, such as cadherin, Alzheimer's disease, and angiogenesis signaling, highlighted to be associated with WBP2 in this proteogenomic study have yet been explored." (PMID 34197030, 2022). "Our in silico analysis implicated WBP2 in neurological disorders like Huntington’s and Alzheimer’s disease." (PMID 32393834, 2020).
hepatocellular carcinoma (2 papers, 2021 to 2024). A malignant tumor that arises from hepatocytes. "There is a higher expression of WBP2 in hepatocellular carcinoma cells than in normal liver cells, and downregulation of WBP2 blocks the activation of the Wnt/β-catenin signaling pathway." (PMID 38239300, 2024).
Insulin resistance (2 papers, 2020 to 2021). Increased resistance towards insulin, that is, diminished effectiveness of insulin in reducing blood glucose levels. "Finally, USF-1-mediated regulation of WBP2 in response to insulin stimulation raises the possibility of WBP2’s involvement in insulin signaling-related diseases such as insulin resistance and diabetes." (PMID 32393834, 2020). "Overexpression of WBP2 with AAV in vivo alleviated liver fat deposition and insulin resistance induced by a high-fat diet (HFD)." (PMID 33658485, 2021). "Knockdown of WBP2 with AAV aggravated HFD-induced fatty liver and insulin resistance." (PMID 33658485, 2021).
ovarian carcinoma (2 papers, 2017 to 2022). A malignant neoplasm originating from the surface ovarian epithelium. "WBP2 may participate in the development of some uterine and ovarian cancer diseases that have a strong relationship with ER." (PMID 28724435, 2017).
adenomyosis (1 paper, 2024). The growth of endometrial tissue inside the muscular wall of the uterine corpus. "The results of this study indicated that WBP2 expression was positively correlated with COX-2 in adenomyosis tissues." (PMID 38239300, 2024). "WBP2 also regulates ER expression in an estrogen-dependent manner, and high ER expression and abnormal activation of the Wnt signaling pathway may be important factors in the pathogenesis of adenomyosis." (PMID 38239300, 2024). "COX-2, IFITM3, SFRP4, and WBP2 may be involved in the pathogenesis of adenomyosis." (PMID 38239300, 2024). "In ectopic endometrium of adenomyosis, the expression levels of COX-2 were positively correlated with the expressions of WBP2, IFITM3, and SFRP4 (r = 0.536, P < 0.01; r = 0.591, P < 0.01; r = 0.533, P < 0.01)." (PMID 38239300, 2024). "This study demonstrated that COX-2, WBP2, IFITM3, and SRFP4 may be involved in the pathogenesis of adenomyosis." (PMID 38239300, 2024). "WBP2 and SFRP4 were significantly expressed in the cytoplasm and cytosol of glandular cells in the ectopic endometrium of adenomyosis, but not in the myometrium and the mesenchymal cells of ectopic endometrium." (PMID 38239300, 2024). "Thus, the expression of COX-2, WBP2, IFITM3, and SFRP4 did not correlate significantly with menstrual flow and volume in adenomyosis." (PMID 38239300, 2024).
breast disease (1 paper, 2017). "Other WW-domain-containing proteins may interact with WBP2 to function in human breast disease or other diseases." (PMID 28724435, 2017).
chronic myelogenous leukemia (1 paper, 2017). "WBP-2 localizes on the chromosome 17q25 region, which is known as being involved in certain forms of human carcinogenesis, such as chronic myelogenous leukemia (CML)." (PMID 28724435, 2017).
deafness (1 paper, 2016). An inherited or acquired condition characterized by the complete loss of the ability to hear from one or both ears. "We reported the cases of two children affected by severe to profound deafness, each carrying two variants in heterozygosis in the WBP2 gene." (PMID 26881968, 2016). "Moreover, we report the cases of a 5‐year‐old boy and a 9‐year‐old girl with severe to profound prelingual deafness, each carrying two point variants in heterozygosis in the WBP2 gene." (PMID 26881968, 2016). "The second child has a second variant in exon 5, and although the predictions for the two exon 5 variants are less deleterious, the importance of this exon for the organ of Corti supports our conclusion that the deficiency in WBP2 is the cause of the deafness observed in these children." (PMID 26881968, 2016). "Following the discovery of Wbp2 as a new gene involved in deafness in the mouse, the human WBP2 gene was included in a screen of 8,087 deaf probands and 1,823 unaffected controls in China using targeted next‐generation sequencing." (PMID 26881968, 2016).
Dysmenorrhea (1 paper, 2024). Pain during menstruation that interferes with daily activities. "WBP2 expression was not significantly correlated with dysmenorrhea symptoms, while COX-2 was strongly associated with dysmenorrhea, therefore WBP2 may be regulated by the Wnt protein, but not by COX-2." (PMID 38239300, 2024). "The relationship between dysmenorrhea and expression of COX-2, WBP2, IFITM3, and SFRP4." (PMID 38239300, 2024).
fatty liver (1 paper, 2021). "The data above demonstrated that WBP2 hepatocyte deficiency could exacerbate HFD-induced fatty liver and IR." (PMID 33658485, 2021). "Considering the important role of AMPK in various metabolic diseases, whether the protective effect of WBP2 on the fatty liver is mediated through the AMPK pathway remains unclear." (PMID 33658485, 2021). "To determine whether WBP2 is involved in the occurrence and development of fatty liver, we tested the expression of WBP2 in the livers of the mice with NAFLD." (PMID 33658485, 2021). "Our study found that the expression of WBP2 decreased in the fatty liver due to a HFD, and overexpression of WBP2 reduced fatty liver and IR." (PMID 33658485, 2021).
glioblastoma (1 paper, 2018). The most malignant astrocytic tumor (WHO grade IV). "Further studies are needed to determine the precise mechanism by which WBP2 acts on a molecular level in the EMP pathway, indicating a novel therapeutic target for glioblastoma treatment." (PMID 29497031, 2018).
leukoaraiosis (1 paper, 2018). "Genome-wide association studies of cerebral white matter lesions indicate that WBP2 gene is high risk for leukoaraiosis, suggesting that WBP2 might be a key regulator of nervous system inflammation." (PMID 29497031, 2018).
lymph node metastasis (1 paper, 2021). "Notably, WBP2 expression in patients with lymph node metastasis was significantly higher than that observed in patients without lymph node metastasis (44.7 vs 70.6%, P < 0.05)." (PMID 33837178, 2021).
metastatic cancer (1 paper, 2020). A carcinoma which has spread from the original site of growth to another anatomic site. "That aberrant WBP2 expression could be detected in DCIS, a preneoplastic lesion, and its elevated levels in invasive/metastatic cancer suggest that WBP2 plays a role in disease initiation and progression." (PMID 32393834, 2020).
oral cancer (1 paper, 2020). "WBP2 is involved in an increasing number of signaling pathways, human cancers, and even canine oral cancer." (PMID 32393834, 2020).